IGF1 (insulin like growth factor 1)
Diseases named in the same sentence as IGF1 in open-access papers (continued):
Sharing a sentence is not in itself a finding about the gene and the disease.
metabolic syndrome (188 papers, 2008 to 2026). A cluster of metabolic risk factors for CARDIOVASCULAR DISEASES and TYPE 2 DIABETES MELLITUS. "Meanwhile, some studies have shown that low levels of IGF-1 are associated with the components of metabolic syndrome, including elevated triglycerides and reduced HDL cholesterol levels, which is consistent with our findings." (PMID 40538800, 2025). "Parallel epidemiologic data indicate that individuals with higher interleukin-6 (IL-6) and lower IGF-1 levels face an elevated risk of metabolic syndrome." (PMID 41393761, 2025). "Children with a higher BMI z-score had a higher risk of being in the “inflammation” and “dyslipidemia/high leptin” status and a lower chance of being in the “low leptin/IGF-1/HbA1c” status at age 8 with the effects again increasing with age." (PMID 39899498, 2025). "The underlying etiology is thought to be the activation of IGF-1 leading to inhibition of apoptosis and dyslipidemia leading to proinflammatory cytokines and the accumulation of TG in intestinal cells." (PMID 38706995, 2024). "Reductions in circulating IGF1 and hypovitaminosis D, and a range of IGF1 binding proteins, have been found to be associated with metabolic syndrome and its components." (PMID 37892272, 2023). "To next identify the factor most strongly associated with low IGF-1 levels among increased adiposity, inflammation and high frequencies of dyslipidemia and hyperuricemia, we conducted stepwise variable selection." (PMID 36418379, 2022). "Four reliable variables associated with the low IGF-1 group (P < 0.05) (body fat percentage, dyslipidemia, hyperuricemia and natural log-transformed HS-CRP) were enrolled and we applied the forward–backward stepwise variable selection procedure." (PMID 36418379, 2022). "Data were analyzed to identify associations between IGF-1 genotypes and patient biochemical parameters, including the components of metabolic syndrome and the long-term change in renal function." (PMID 34078313, 2021). "Our data are aligned with the documented role of IGF-1 deficiency in the pathophysiology of both cardiovascular conditions and metabolic syndrome." (PMID 33807089, 2021). "In secondary analyses, we explored the associations of genetically predicted IGF-1 levels with components of the metabolic syndrome." (PMID 32548700, 2020). "We included IGF-1 as an endpoint in this study due to associations of this hormone with cancer risk and metabolic syndrome." (PMID 31191190, 2019). "From this viewpoint we regard the significant elevation of IGF-1 in a low baseline IGF-1 subgroup as a positive change, which is possibly associated with a reduced risk of developing the metabolic syndrome and with improved insulin sensitivity." (PMID 31191190, 2019). "As well, this experimental model is suitable for studying cardiac disease mechanisms and exploring therapeutic options for patients under IGF-1 deficiency conditions such as ageing, metabolic syndrome, advanced cirrhosis." (PMID 28806738, 2017). "It was observed that high-normal IGF-1 levels were associated with the metabolic syndrome and high triglyceride levels." (PMID 27544533, 2016). "In this review we discuss the relevant actions of IGF-1 on metabolism and the implication of IGF-1 deficiency in the establishment of metabolic syndrome." (PMID 26733412, 2016). "In support of this thesis, evidence suggests that the mechanisms underlying the association between pre-diabetes/metabolic syndrome and cancer incidence involves the influence of elevated insulin and IGF-1." (PMID 23405181, 2013). "IGF1, which encodes insulin-like growth factor 1, is associated with cardiovascular disorders, metabolic syndrome, decreased body weight/size, and changes of insulin levels in mice." (PMID 22479346, 2012). "Elevated levels of triglycerides, insulin, glucose, and IGF-1 have all been suggested as contributing to the association of the metabolic syndrome with increased risk of colorectal cancer." (PMID 22127286, 2012).
metabolic syndrome (continued). "The CCS with a higher fat-to-lean mass ratio (FLR) values demonstrate increased trunk fat, elevated triglycerides, and insulin resistance, alongside lower lean mass and IGF-1 levels-factors that collectively predispose survivors to the risk of metabolic syndrome and cardiovascular issues." (PMID 41374948, 2025). "Unexpectedly, a longer total breast-feeding duration was associated with a higher risk of being in the “inflammation” (1.04 [1.01;1.07]), “dyslipidemia/high leptin” (1.07 [1.03;1.11]) as well as “low leptin/IGF-1/HbA1c” status (1.06 [1.02;1.11]) as compared to the “normal” status." (PMID 39899498, 2025). "Next, using the entire subjects of this study, we aimed at identifying the factor most strongly associated with low IGF-1 levels among those showing statistically significant relevance (i.e. increased adiposity, dyslipidemia, hyperuricemia and increased inflammation)." (PMID 36418379, 2022). "This study investigated whether the single-nucleotide polymorphism of IGF-1, rs35767, plays a role in metabolic syndrome indicators, including blood pressure, glucose metabolism, uric acid levels, and renal function." (PMID 34078313, 2021). "This study investigates whether the IGF-1 gene polymorphism rs35767 is associated with metabolic syndrome indicators, including BP and glycated hemoglobin (HbA1c)." (PMID 34078313, 2021). "Accordingly, normal IGF-1 levels were linked with a lower prevalence of metabolic syndrome." (PMID 32655494, 2020). "Moreover, compared to patients with a normal VAI, high VAI patients had higher GH and IGF-1 values, and a lower insulin sensitivity and adiponectin concentration, suggesting proneness to metabolic syndrome and CV risk." (PMID 29036907, 2017). "Respondents with the metabolic syndrome and high IGF-1 levels had an increased risk of CVD." (PMID 27544533, 2016). "Furthermore, the role of the metabolic syndrome in the association between IGF-1 and incident cardiovascular disease (CVD) was studied." (PMID 27544533, 2016). "Can insulin-like growth factor-1 deficiency be involved in metabolic syndrome establishment?" (PMID 26733412, 2016). "Consistent evidence associates IGF-1 deficiency and metabolic syndrome." (PMID 26733412, 2016). "As the component of metabolic syndrome, low HDL-C may be partially accounted for the association between IGF-1 and risk of metabolic syndrome." (PMID 27343122, 2016). "Other potential mechanisms by which fatty liver may increase cardiovascular risk beyond that imposed by the metabolic syndrome are lipotoxicity and increased circulating IGF-1 and IGFBP-3." (PMID 23924883, 2013). "Thus, this work aimed to link the consequences of chronically low levels of IGF-1 and acute liver damage, as several conditions resemble such a deficiency (metabolic syndrome, aging...), which could render individuals more sensible to liver aggression." (PMID 28472963, 2017). "The “inflammation” group in our study was characterized by slightly higher BMI than the “normal” and “low leptin/IGF-1/HbA1c” group but lower BMI as compared to the “dyslipidemia/high leptin” group." (PMID 39899498, 2025). "The biomarker status “dyslipidemia/high leptin” was characterized by higher triglycerides, leptin, IGF-1 and lower HDL-cholesterol concentrations as compared to the “normal” status." (PMID 39899498, 2025). "Lab results show prediabetes (HbA1c 5.85%), hyperuricemia, dyslipidemia, and elevated IGF-1 (646.7 ng/mL)." (PMID 40428329, 2025). "Longer total breast-feeding duration increased the likelihood for being in the “inflammation”, “dyslipidemia & high leptin” and “low leptin/IGF-1/HbA1c” status compared to the “normal” status in our study." (PMID 39899498, 2025). "This is in line with the (non-significant) higher probability of pubertal children being in the “dyslipidemia & high leptin” status and lower probability of being in the “low leptin/IGF-1/HbA1c” status in our study." (PMID 39899498, 2025).
metabolic syndrome (continued). "IGF-1 levels are influenced by age, metabolic syndrome, nutritional intake, IGFBP-mediated bioavailability, and hormonal status, while laboratory assays and sampling times varied widely among included studies." (PMID 41586110, 2025). "These include a BMI of 44.68 kg/m2, “buffalo hump”, prediabetes (HbA1c 5.85%), insulin levels fourfold above normal, dyslipidemia, and elevated IGF-1 (646.7 ng/mL)." (PMID 40428329, 2025). "The mean BMI z-score of the child, but also maternal BMI were highest in children in the “dyslipidemia/high leptin” status while being lowest in the “low leptin/IGF-1/HbA1c” status." (PMID 39899498, 2025). "An epidemiologic study demonstrated that a decrease in the serum IGF-1 level correlated most strongly with age, BMI, and metabolic syndrome." (PMID 40141452, 2025). "In our study, we identified four distinct biomarker statuses based on comprehensive data and repeatedly collected blood samples of a large European children cohort including: “normal”, “low leptin/IGF-1/HbA1c”, “inflammation” and “dyslipidemia/high leptin”." (PMID 39899498, 2025). "This study demonstrated that low endogenous glucocorticoid level under PDE lead to liver dysplasia by downregulating the H3K27ac level of IGF1 and its expression, ultimately contributing to metabolic syndrome in adult offspring." (PMID 38263047, 2024). "IGF-1 is a crucial hormone in the pathophysiology of metabolic syndrome as it affects carbohydrate and lipid metabolism." (PMID 36991247, 2023). "Here, we review the evidence for the potential therapeutic effects of IGF-1 in the neurodegeneration related to metabolic syndrome." (PMID 36691085, 2023). "For example, studies have shown that people with high levels of IGF-1 are more likely to develop resistance to insulin and overweight or obesity, both of which are hallmarks of metabolic syndrome." (PMID 38248733, 2023). "Reductions in circulating IGF1 and in some IGF1 binding proteins (especially IGFBP-1), as well as hypovitaminosis D, have been found to be associated with metabolic syndrome and its related components." (PMID 37892272, 2023). "Nevertheless, the precise correlation between IGF-1 and metabolic syndrome remains incompletely comprehended, necessitating further investigation to validate this association." (PMID 38248733, 2023). "By comparing the low and standard IGF-1 groups, obese subjects with low IGF-1 levels were revealed to be predisposed to increased adiposity, inflammation and metabolic disorders (dyslipidemia and hyperuricemia)." (PMID 36418379, 2022). "The most recognized partial IGF-1 deficiency conditions are cirrhosis, FGR, aging, and metabolic syndrome." (PMID 36138743, 2022). "We also revealed clinical characteristics of obese patients with low IGF-1 levels, i.e. increased adiposity and inflammation and metabolic comorbidities, such as dyslipidemia and hyperuricemia." (PMID 36418379, 2022). "IGF-1 is a crucial hormone in the development of metabolic syndrome, due to its influence on lipid and carbohydrate metabolism." (PMID 35627568, 2022). "This indicates IGF-1 plays a major role in the pathophysiology of both cardiovascular disease and metabolic syndrome and, therefore, potentially in radiation-induced early or late health effects." (PMID 33807089, 2021). "Insulin-like growth factor-1 (IGF-1) signaling perturbations are implicated in development of cardiovascular disease and metabolic syndrome." (PMID 33807089, 2021). "IGF-1 is a hormone that is closely related to metabolic syndrome and is mainly secreted by the liver cells." (PMID 35198620, 2021). "The lower serum IGF-1 levels and vulnerability to metabolic syndrome in GMP potentially reflects the disturbance of insulin and IGF-1 signaling." (PMID 32708958, 2020). "Results from the Framingham heart study showed a dose-response relationship between lowering in IGF-1 values and the number of abnormalities of metabolic syndrome factors." (PMID 32655494, 2020).
metabolic syndrome (continued). "On the other hand, there are four variables in both models with a decreasing effect on the hazard ratio if their value is increased (intake of drugs to treat benign prostatic hypertrophy, treated dyslipidemia, IGF-1 and female sex)." (PMID 28422991, 2017). "In turn, four variables were found to be associated with decreased mortality rates: treatment of benign prostatic hypertrophy, treatment of dyslipidemia, IGF-1 and being female." (PMID 28422991, 2017). "This is the first study in obese children concerning IGF-1 and metabolic syndrome and its components." (PMID 27343122, 2016). "Based on the available data we propose IGF-1 as a key hormone in the pathophysiology of metabolic syndrome; due to its implications in the metabolism of carbohydrates and lipids." (PMID 26733412, 2016). "IGF-1 concentrations were reported as influenced by age, adiposity, serum glucose, and metabolic syndrome." (PMID 23405181, 2013). "Metabolic complications, mainly dyslipidemia, are frequent in cured acromegalic patients, but GH/IGF-1 discrepancy does not seem to represent a risk factor for their presence or persistence." (PMID 37829686, 2023). "Finally, consistent evidence exists for the inverse relationship of IGF-1 levels and metabolic syndrome, with very low IGF-1 accompanied to metabolic syndrome." (PMID 36768692, 2023). "In conclusion, our study underlines, with a real-life approach, that GH/IGF-1 incongruence does not seem to represent a higher risk of metabolic complications, even dyslipidemia, in acromegalic patients, with results aligned with other recent studies." (PMID 37829686, 2023). "In T2D, insulin resistance and altered IGF-1/IGF-1R signaling are associated with cognitive decline, Aβ production, tau hyperphosphorylation, proinflammatory marker’s expression, oxidative stress, and dyslipidemia." (PMID 36691085, 2023). "Furthermore, studies investigated the relationship between circulating IGF-1 concentrations and metabolic syndrome." (PMID 36691085, 2023). "The frequencies of dyslipidemia (16 (94.1%) vs. 30 (63.8%), P = 0.025) and hyperuricemia (15 (88.2%) vs. 19 (40.4%), P < 0.001) were significantly higher in the low than in the standard IGF-1 group." (PMID 36418379, 2022). "Whereas some researchers reported elevated IGF-1 levels in obese compared with lean or overweight people, several studies presented lower IGF-1 serum levels in association with higher fat mass and components of the metabolic syndrome." (PMID 34636987, 2022). "For example, calcitriol suppresses the secretion of pro-inflammatory cytokines, stimulates the secretion of anti-inflammatory cytokines from macrophage-infiltrated adipose tissue, and upregulates insulin growth factor 1 (IGF-1) secretion, which has protective effects against metabolic syndrome." (PMID 35967768, 2022). "In addition, the frequency of dyslipidemia tended to be higher in the low IGF-1 group (5 (100.0%) vs. 7 (38.9%), P = 0.11)." (PMID 36418379, 2022). "Furthermore, natural log-transformed high-sensitivity C-reactive protein, and the frequencies of dyslipidemia and hyperuricemia were higher in the low IGF-1 group." (PMID 36418379, 2022). "Collectively, these observations indicate that, despite their similar BMI, obese subjects with low IGF-1 levels are markedly more predisposed to have multiple metabolic abnormalities, such as increased adiposity, inflammation, dyslipidemia and hyperuricemia than subjects in the standard IGF-1 range." (PMID 36418379, 2022). "The insulin/IGF-1/AKT pathway is a key event linking metabolic syndrome with endometrial cancer." (PMID 36497428, 2022). "Central obesity promotes sleep apnea through mechanical action and low-grade inflammation, while OSAS promotes metabolic syndrome through sympathetic nervous overactivity, reactive oxygen production, low-grade inflammation, and alterations in cortisol and IGF-1 circadian fluctuations." (PMID 31684029, 2019).
metabolic syndrome (continued). "Circulating levels of IGF-1 may decrease under several circumstances like ageing, metabolic syndrome, and advanced cirrhosis." (PMID 28806738, 2017). "For example, in a study of the effects of the interaction of IGF-1 with 25(OH)D in metabolic syndrome, individuals with higher levels of both vitamin D and IGF-1 had lower prevalence of metabolic syndrome, but this benefit was only seen up to a 25(OH)D threshold of 75–85 nmol/L." (PMID 28417914, 2017). "As this work reveals, not only prepubescent individuals suffering from this condition should be medicated with IGF‐1, but also adults could be provided with it to avoid dramatic complications derived from the long progression of metabolic syndrome." (PMID 29152285, 2017). "There is an independent association among lower IGF-1, low HDL-C and metabolic syndrome." (PMID 27343122, 2016). "Our results showed that children classified as “low leptin/IGF-1/HbA1c” had the highest probability to stay in that group whereas e.g. children from the “normal group” had a non-negligible risk of drifting into the “dyslipidemia/high leptin” group." (PMID 39899498, 2025). "There is some evidence that IGF-1 may contribute to the onset of metabolic syndrome." (PMID 38248733, 2023). "At the turn of the century, some studies suggested that low IGF-I levels were associated with increased ischemic heart disease and that IGF-1 protects against endothelial dysfunction, atherosclerotic plaque development, metabolic syndrome, clinical instability, and ischemic myocardial damage." (PMID 29712555, 2018). "Importantly, the inverse relationship remains significant after adjustment for several confounders potentially affecting either circulating IGF-1 or fasting glucagon levels, including age, gender, adiposity, insulin sensitivity, dyslipidemia and glucose tolerance status." (PMID 28881681, 2017). "Moreover, we showed that regulation of the Sirt1-PPARα-IGFBP-2 signaling cascade by AMPK activator represents a novel pathway that could be applied to ameliorate metabolic syndromes by controlling IGF-1 homeostasis." (PMID 27009398, 2016). "An inverse relationship between IGF-1 levels and the prevalence of Metabolic Syndrome (MetS) with its cardiovascular complications has been identified." (PMID 26467524, 2015). "The risk of having left ventricular hypertrophy (crude odds ratio) for the metabolic syndrome and its different components and insulin as well as physical activity, oestrogen and percentile levels of insulin-like growth factor binding protein-1 and insulin-like growth factor-1." (PMID 25461385, 2014). "SPP1, CD44, IGF1, and FLT1 were identified as crucial molecules in the main cluster of Alzheimer’s disease and metabolic syndrome." (PMID 38809924, 2024). "Our analysis identified four essential genes—SPP1, IGF1, CD44, and FLT1—that serve as potential molecular links between Alzheimer’s and metabolic syndrome." (PMID 38809924, 2024). "Ad-MSC expression of miR-155 appears blunted in visceral obesity, which correlates with Ad-MSC IGF-1 hypersecretion and IL-10 hyposecretion, systemic microinflammation, and HDL dyslipidemia." (PMID 38928349, 2024). "While insulin-like growth factor 1 (IGF-1) exerts a cardioprotective effect in the setting of atherosclerosis, insulin-like growth factor binding protein 2 (IGFBP-2) is involved in metabolic syndrome." (PMID 36970368, 2023). "The simultaneous reduction in glucose, insulin, and IGF1 and the increase in IGFBP1 seen postoperatively, and remaining at follow-up, strengthen the possible reversibility of the metabolic syndrome coupled with PHPT." (PMID 24026893, 2013). "While univariate analysis confirmed a significant negative association between IGF-1 SDS and RHI, this relationship weakened in multivariate models after adjustment for adiposity indices and key biochemical markers of metabolic syndrome." (PMID 41374948, 2025).